TOP2A (DNA topoisomerase II alpha)
Diseases named in the same sentence as TOP2A in open-access papers (continued):
Sharing a sentence is not in itself a finding about the gene and the disease.
cancer (continued). "Additionally, TOP2A is a risk factor for poor survival and a reliable prognostic biomarker in different cancers to predict cancer progression and relapse." (PMID 36585615, 2022). "Moreover, TOP2A expression was found to be associated with the cancer-associated immune cell infiltration, including fibroblasts, Tregs, and macrophages." (PMID 35873470, 2022). "Pan-cancer analysis of TOP2A, in terms of association with the clinical prognosis and involved molecular mechanisms based on profiling data, is necessary to understand the tumorigenesis mechanisms and explore the potential diagnostic biomarkers and treatment targets in clinical practice." (PMID 35873470, 2022). "Over expression of TOP2A is responsible for growth of cancer, but increase expression of this gene might associate with growth of pituitary prolactinoma." (PMID 33709028, 2021). "Moreover, TOP2A (DNA topoisomerase II alpha) encodes a DNA topoisomerase which is a well-studied cancer-associated protein." (PMID 32149105, 2020). "Despite the well-known association between TOP2A expression and aggressiveness of different cancers, the underlying role of TOP2A in the BLCA remains unclear." (PMID 31216997, 2019). "A similar observation has been made previously in which it was observed that although cells which showed high levels of TOP2A were highly proliferative and associated with metastasis in PCa, cancer stem cells were actually enriched in PCa cells which showed low/negligible levels of TOP2A." (PMID 28410543, 2017). "Genetic alterations in human topoisomerase II alpha (TOP2A) are linked to cancer susceptibility." (PMID 22111588, 2011). "Thus, TOP2A is closely associated with cancer proliferation." (PMID 34298705, 2021). "As etoposide is a TOP2A poison that induce covalent binding of TOP2A protein with DNA and results in DNA break and fragment in cancer cells, the etoposide sensitivity may be associated with the DNA repair mechanism in which the poly (ADP-ribose)polymerase (PARP) cleavage may be involved." (PMID 24103454, 2013). "Anthracyclines are potent chemotherapeutic agents known for their efficacy in treating various cancers via inhibition of topoisomerase II α (TOP2A)." (PMID 42102394, 2026). "STUB1 inhibited TOP2A’s activity, reduced cancer cell proliferation, increased doxorubicin-induced apoptosis, and promoted cell cycle arrest." (PMID 41851614, 2026). "TOP2A is an important target for cancer drug development, with inhibitors such as doxorubicin and epirubicin being used in chemotherapy." (PMID 40777026, 2025). "DS score detected 106 upregulated ER genes as well as 71 downregulated ER genes in at least two cancer types, where the most recurrently upregulated ER gene in the TCGA cancer types was TOP2A." (PMID 41431699, 2025). "High expression of TOP2A has been correlated with poor prognosis in various cancers, including breast, prostate, and ovarian malignancies." (PMID 41162745, 2025). "Despite these advances, challenges remain in translating these findings into clinical practice, necessitating further investigation into the complex interplay between TOP2A status and cancer biology." (PMID 40290723, 2025). "Anthracyclines induce their potent anti-cancer effects primarily via TOP2A, but at the same time they induce a dose limiting cardiotoxicity through TOP2B." (PMID 40425539, 2025). "In contrast, higher levels of TOP2A imply an active proliferative state of cancer cells, which can enhance tumor aggressiveness and lead to disease progression, resulting in poor prognosis and increased risk of death." (PMID 41284119, 2025). "TOP2A is also a target for many drugs that fight cancer, such as anthracyclines, epipodophyllotoxins, and bisdioxopiperazines." (PMID 41439111, 2025).
cancer (continued). "TOP2A+ epithelial cells are primarily enriched in the cell cycle and DNA replication pathways, indicating proliferative cancer cells." (PMID 40520021, 2025). "Topoisomerase II alpha (TOP2A), an enzyme critical for DNA replication and cell division, has attracted considerable attention in cancer research due to its pivotal role in tumor development and its potential as a therapeutic target." (PMID 40290723, 2025). "It is possible that the elevated levels of TOP2A in cancer cells is one of the contributing factors in the preference of poxviruses for infecting tumors." (PMID 40557872, 2025). "Extensive research has highlighted the importance of TOP2A in cancer cell proliferation and its potential as a therapeutic target." (PMID 40290723, 2025). "This TOP2A-MYC interaction supports high transcriptional demands in cancer cells, though excessive activity triggers DNA damage through DSBs." (PMID 41273720, 2025). "Overexpression of TOP2A and POLA2 has been strongly associated with enhanced cancer cell proliferation, and the observed downregulation of these proteins following ST1926 treatment indicates a potential reduction in cellular proliferation activity." (PMID 40429796, 2025). "TOP2A is often overexpressed or amplified in many cancers and indicates how will the cancer cells respond to the drugs that target TOP2A." (PMID 41439111, 2025). "Though mammalian cells express an A and B isoform of Top2, we focus on the Top2A isoform, as cancer cells that are highly proliferative would have increased dependence on Top2A50,54." (PMID 40585230, 2025). "In hTERT-RPE1 cells and other non-cancer cell models, prolonged G2 arrest is triggered upon catalytic inhibition of TOP2A." (PMID 39885205, 2025). "The enzyme TOP2A is essential for overcoming topological issues during DNA replication, transcription, and repair, and has been recognized as a target for cancer treatment." (PMID 41301416, 2025). "The overexpression of TOP2A was considered as a key biomarker of various cancers, including ovarian and lung." (PMID 39908244, 2025). "TOP2A is an important regulator in transcription and cancer by regulating chromatin topology and maintaining genomic integrity." (PMID 41000417, 2025). "TOP2A gene is highly expressed in proliferative cells and clue that it is involved in aggressive invasive behaviors of cancer cells." (PMID 38561479, 2024). "As for its role in cancer, TOP2A expression showed an aberrant gain in NSCLC tissues compared to normal tissues, and TOP2A was associated with worse NSCLC patients’ survival." (PMID 38374109, 2024). "Given that cancer is characterized by uncontrolled cell growth and division, enzymes like TOP2A that are essential for DNA replication are often found to be overexpressed in various tumor types." (PMID 38730293, 2024). "DNA topoisomerase II alpha (TOP2A) expression, gene alterations, and enzyme activity have been studied in various malignant tumors." (PMID 38806610, 2024). "Mechanistic studies have elucidated that TOP2A modulates key signaling pathways, which are pivotal in cancer cell growth and survival." (PMID 39727717, 2024). "DNA topoisomerase IIA (TOP2A) plays a significant role in the development, progression, invasion, treatment, and prognosis of cancerous tumors." (PMID 38806610, 2024). "DNA Topoisomerase IIα (Top2A) is a nuclear enzyme that is a cancer drug target, and there is interest in identifying novel sites on the enzyme to inhibit cancer cells more selectively and to reduce off-target toxicity." (PMID 38891861, 2024). "TOP2A has been reported to be a sensitive and specific marker of active proliferating cells, indicating its importance in cancer research." (PMID 39234567, 2024). "In conclusion, our results demonstrated that TOP2A accelerates cancer progression in NSCLC, and this impact is intimately associated with the EMT process." (PMID 38806610, 2024).
cancer (continued). "Inhibition of TOP2A has been explored as a potential therapeutic strategy for cancer treatment, as it can disrupt DNA replication and induce cell death (Uusküla-Reimand & Wilson, 2022)." (PMID 38250721, 2024). "The enzyme topoisomerase II alpha (TOP2A) plays a critical role in DNA replication and cell proliferation, making it a promising target for cancer therapy." (PMID 39727717, 2024). "TOP2A, as a target of chemotherapy drugs, has been proven to be widely involved in the invasion and prognosis of various human cancers." (PMID 38464517, 2024). "The role of TOP2A has been studied to varying degrees in different cancer types, and it is overexpressed in a variety of solid tumors, particularly during tumorigenesis." (PMID 38806610, 2024). "Top2a has traditionally served as a marker for proliferation in both normal and cancer tissues, and Uhrf1 is recognized as a known positive regulator of Top2a activity." (PMID 39544362, 2024). "Topoisomerase IIα (TOP2A), is an enzyme involved in DNA replication, transcription, recombination, and chromatin remodeling and is found in a variety of cancers." (PMID 38957610, 2024). "Beyond their essential physiological activities, TOP2α and TOP2β are treatment targets for widely prescribed anti-cancer medications, particularly, TOP2 poisons, including etoposide, doxorubicin, and teniposide." (PMID 38263255, 2024). "In cancer, the role of TOP2A is of particular interest because of its involvement in the proliferation of cells." (PMID 38730293, 2024). "TOP2A has been demonstrated to be involved in mechanisms of cancer formation and can be used as a biological predictor in a number of studies." (PMID 38467737, 2024). "Overexpression of TOP2A occurs in a variety of cancers and participates in carcinogenesis through multiple pathways." (PMID 39063036, 2024). "TOP2A is a known key enzyme in DNA replication, cancer cell proliferation and a direct or indirect target of several cytotoxic anticancer agents (e.g. anthracyclines and etoposides)." (PMID 37880313, 2023). "In contrast, expression of AURKB and TOP2A (cell cycle genes) in cancer cells was significantly downregulated after pembrolizumab treatment, indicating a reduction in cancer-cell proliferation." (PMID 36973261, 2023). "There are two major forms of topoisomerase-2 (Top2); Top2α is only expressed in proliferating cells and is widely regarded as the main target of doxorubicin's anti-cancer effects, while Top2β is present in all mammalian cells including cardiomyocytes." (PMID 37745115, 2023). "Cancer cell subcluster 2 also expressed high levels of cell proliferation markers (TOP2A and CCND2) and a goblet cell marker (CLCA1)." (PMID 36690709, 2023). "HIF (and TOP2A) is elevated in several types of malignant tumors, which make this possible connection relevant in many other types of tumors as well." (PMID 36656469, 2023). "For example, the miR-139/TOP2A/β-catenin axis was identified as a biomarker for diagnosis and became a valid therapeutic target for cancer treatment." (PMID 37048139, 2023). "Highly expressed TOP2A is involved in many cancers, with its expression estimated to be elevated or deregulated in the majority of human cancers." (PMID 37244966, 2023). "Among them, we showed that the anthracycline antibiotics and classic cancer chemotherapeutics (i) doxorubicin, (ii) daunorubicin, and (iii) idarubicin are predicted to be able to reverse TOP2A upregulation." (PMID 38067357, 2023). "The TOP2A gene matched with eight drugs, and they are adopted for cancer therapy, among the matches between the input hub genes and the selected drugs." (PMID 37808164, 2023). "Insight into the action of the activated form of AQ4N can be found in its structural similarity to mitoxantrone (MTX), an anti‐cancer DNA intercalator and TOP2A poison." (PMID 35499745, 2023).
cancer (continued). "TOP2A, a highly expressed gene in various types of carcinomas, is valuable in diagnosing cancer, monitoring disease progression, and predicting prognosis." (PMID 37383715, 2023). "To explore the role of TOP2A in cancers, we further evaluated TOP2A expression in various tumors and adjacent normal tissues." (PMID 37980167, 2023). "TOP2A has been suggested as a marker of poor prognosis and a potential therapeutic marker in several other cancer types, which make a similar mechanism in PPGL plausible." (PMID 36656469, 2023). "In contrast, TOP2α is typically expressed in quickly growing cancer cells and is essential for cell growth." (PMID 36650267, 2023). "Top2α is the primary molecular target for Top2 poison activity and Top2α expression levels are used as a prognostic biomarker for screening cancer patients suitable for Top2 poison treatment." (PMID 37528151, 2023). "Ofloxacin produced the weakest effect on both topoisomerase isoenzymes in the cancer cell lines, while in the case of non-cancer cells, this effect was observed in the TOP2A gene of the enrofloxacin group." (PMID 37534254, 2023). "For instance, one study demonstrated that the in vitro anti-cancer activity of double strand breaks (DSB) of DOX was mediated by both topoisomerase II alpha (TOP2A) and topoisomerase II beta (TOP2B) isoforms in HTETOP fibrosarcoma cell line." (PMID 37927589, 2023). "In TOP2A vaccinated mice, tumors developed in only 27% of mice, whereas all adjuvant-treated controls developed cancer." (PMID 37880313, 2023). "Pan-cancer analysis of the TCGA database confirmed that the abnormally high expression of TOP2A in a variety of tumors was related to the poor prognosis of LIHC patients, uncovering the role of TOP2A as an oncogene." (PMID 37980167, 2023). "Top2 is the main target for doxorubicin, and it has two forms, Top2α, expressed by highly proliferating cells such as cancer cells, and Top2β, expressed by quiescent cells such as cardiomyocytes." (PMID 37626782, 2023). "TOP2A, an essential regulator for separating replicated chromosomes and a proven therapeutic target of various cancers, showed the highest enrichment in the NT." (PMID 37063610, 2023). "Univariate Cox regression analysis showed that high expression of TOP2A was a factor affecting cancer-specific survival, PFS and recurrence-free survival of BLCA patients." (PMID 35646063, 2022). "TOP2A and RRM1 are abnormally expressed in different types of cancers and are associated with cancer development." (PMID 35711974, 2022). "DNA topoisomerase (TOP2A) has an important relationship with the occurrence, development, invasion, treatment, and prognosis of malignant tumors." (PMID 35990843, 2022). "Shortly after the discovery of TOP1 SUMOylation, it was demonstrated that exposure of mammalian cells to teniposide, a TOP2-targeting anti-cancer drug, resulted in SUMO-1 modification of both TOP2α and TOP2β." (PMID 35463961, 2022). "TOP2α inhibitors/poisons stabilize TOP2α-DNA covalent complexes resulting in persistent DNA damage and are frequently utilized to treat a variety of cancers." (PMID 35804920, 2022). "Our work of TOP2A pan-analysis contributes to understanding the prognostic and immunological roles and potential upstream molecular mechanism of TOP2A in different cancers." (PMID 35778520, 2022). "Our results showed that among the 10953 cancer patients, 381 cases appeared with TOP2A alteration with a frequency of 3% (381/10953), and amplification was the main genetic alteration type of TOP2A." (PMID 35873470, 2022). "Our analysis corroborated that TOP2A was overexpressed in all 18 cancer types with enough normal tissues from TCGA project." (PMID 35778520, 2022). "The overexpression of TOP2A was also existed in most cancers when we added the normal tissues from GTEx program." (PMID 35778520, 2022).
cancer (continued). "As a marker of proliferation and chemotherapy resistance, a higher TOP2A level was indicative of poor prognosis in many human cancers and also the target for some most widely used anti-cancer drugs." (PMID 35444699, 2022). "As a key catalytic enzyme in the initiation of DNA replication, TOP2A has been widely recognised as a potential target for cancer therapy." (PMID 35912241, 2022). "Firstly, TIMER database was used to study TOP2A, and the differential expression of TOP2A gene between normal tissues and cancer tissues was analyzed, as well as the correlation between TOP2A gene expression and immune infiltration of HCC cells." (PMID 35033076, 2022). "From the results of these databases, it can be concluded that TOP2A is highly expressed in cancer tissues and low expressed in normal tissues." (PMID 35033076, 2022). "There are two isoforms of the Top2 enzyme: Top2α, which is found mostly in proliferating cells such as cancer cells, and Top2β, which is present predominantly in quiescent cells such as cardiomyocytes." (PMID 35965684, 2022). "Topoisomerase II alpha (TOP2A), highly expressed in various human cancers, is a potential prognostic and predictive marker as well as a therapeutic target in combating HCC." (PMID 35677427, 2022). "High TOP2A expression patients had poorer cancer-specific, progression-free and recurrence-free survival." (PMID 35711974, 2022). "Silencing β-catenin decreased TOP2A-induced cancer cell proliferation, colony formation, and invasion." (PMID 35012441, 2022). "From the perspective of bone and cartilage changes, CDC20 and TOP2A, which are related to cancer cell proliferation and progression, were recently suggested to play a role in rat bone marrow stem cell osteogenesis and chondrogenesis." (PMID 36700234, 2022). "Our first TOP2A pan-cancer study contributes to understanding the prognostic roles, immunological roles and potential upstream molecular mechanism of TOP2A in different cancers." (PMID 35778520, 2022). "Several studies have reported correlations between TOP2A expression levels and prognosis in some cancer patients and indicated that TOP2A expression is a prognostic factor of cancer." (PMID 35711974, 2022). "Topoisomerase IIβ is not essential for cell survival and proliferation, whereas TOP2A is a cell proliferation biomarker and is overexpressed in several rapidly proliferating cancers, including LUAD." (PMID 35251970, 2022). "This work provides a comprehensive knowledge of TOP2A in different cancers, including carcinogenic function, prognostic values for metastasis, and clinical outcomes." (PMID 35873470, 2022). "Some BIIGs were upregulated in multiple cancer types: Top2a, Mki67, Rrm2, Mcm6, and Spp1 were upregulated in more than eight cancer types, while Emp1, Ptx3, and Socs3 were upregulated in seven cancer types." (PMID 36605216, 2022). "We separated the cancer cases into high-expression group (50%) and low-expression group (50%) according to the expression levels of TOP2A." (PMID 35778520, 2022). "In recent years, increasing studies have found that TOP2A plays an important role in the development of cancer." (PMID 36004205, 2022). "Topoisomerase II alpha (TOP2A) is an important nuclear protein which is found in various types of cancers." (PMID 35069905, 2022). "Increasing studies have revealed the importance of TOP2A in carcinogenesis, metastasis, and prognosis of different human cancers." (PMID 35873470, 2022). "Generally, high expression of TOP2A was related to advanced pathological stages in most cancer types." (PMID 35778520, 2022). "Taken together, our first pan-cancer analyses of TOP2A indicated its widespread over-expression in different cancer types." (PMID 35778520, 2022). "We used the “Survival Plots” module of GEPIA2 to analyze the relationship between TOP2A expression and the clinical prognosis of patients with different cancer types in TCGA project." (PMID 35778520, 2022).